GSDME (gasdermin E)
Diseases named in the same sentence as GSDME in open-access papers (continued):
Sharing a sentence is not in itself a finding about the gene and the disease.
glioma (12 papers, 2019 to 2025). A benign or malignant brain and spinal cord tumor that arises from glial cells (astrocytes, oligodendrocytes, ependymal cells). "The results showed that WHO grade IV, IDH 1/2 wild-type, and high GSDME expression was independently associated with poor prognosis of glioma patients in TCGA." (PMID 34830775, 2021). "GSDME activation generally confers robust antitumor effects across most cancers, with gliomas as a notable exception where outcomes depend on sublytic versus lytic pyroptosis." (PMID 41291696, 2025). "AT7519 notably inhibited glioma cell viability and proliferation in a dose-dependent manner and induced pyroptosis through caspase-3-mediated cleavage of gasdermin E (GSDME)." (PMID 39184045, 2024). "In order to illustrate expression pattern and prognostic role of GSDMD and GSDME in glioma, we conducted further experimental validations." (PMID 34830775, 2021). "We found that glioma patients with high GSMDA, GSDMD and GSDME expression were all associated with shorter overall survival time." (PMID 34830775, 2021). "As Gsdme KO in GB increased the survival rate of mice in our study, we speculated that GSDME might affect cell proliferation and invasion of glioma cells." (PMID 40544161, 2025). "In regard to glioma, several small molecules and drugs, such as galangin (through caspase-3/GSDME axis), benzimidazole (through NF-kB/NLRP3/GSDMD axis), kaempferol (through GSDME and ROS), and AT7519 (through caspase-3 cleavage of GSDME) have shown the capability of inducing pyroptosis." (PMID 41291696, 2025). "While in the CGGA dataset, we found that age (>60 years), WHO grade IV, IDH 1/2 wild-type, high GSDMD and GSDME expression could be used independently to predict the prognosis of gliomas patients." (PMID 34830775, 2021). "In this study, we found that blocking ROS generation could reverse pyroptosis, suggesting that kaempferol induced ROS and further contributing to GSDME-mediated pyroptosis in glioma cells." (PMID 33363136, 2020). "Interestingly, when we used 3-MA to inhibit autophagy, we found that the cleaved form of GSDME was also decreased, suggesting that kaempferol induces pyroptosis through regulating autophagy in glioma cells." (PMID 33363136, 2020). "To determine whether pyroptosis contributes to reduced cell viability in GBM cells, we first examined expression of GSDME in human glioma using the genomic data in TCGA and Rembrandt databases." (PMID 31612107, 2019). "Reduced levels of cleaved gasdermin E (GSDME) were observed as a possible explanation for this phenomenon, suggesting that kaempferol induces pyroptosis by regulating autophagy in glioma cells." (PMID 39062119, 2024). "CASP1 displayed the highest mutation frequency, followed by Gasdermin C (GSDMC), while CASP3, Gasdermin B (GSDMB), Gasdermin E (GSDME), and GZAMB did not display any mutations in glioma samples." (PMID 35620284, 2022). "Results of Western blot analysis revealed that GSDMD, not GSDME was elevated in glioma tissues when compared with non-brain tumor tissues." (PMID 34830775, 2021). "Although GSDMA, GSDMB, and GSDME expression was not significantly correlated with glioma prognosis, it had significantly different levels in different clinical or molecular subtypes, suggesting that their potential value in glioma remains to be investigated." (PMID 35784306, 2022).
head and neck cancer (12 papers, 2021 to 2025). A primary or metastatic malignant neoplasm affecting the head and neck. "The natural product triptolide, which exerts potent antitumor activity, has been confirmed to induce GSDME-mediated pyroptosis in head and neck cancer." (PMID 38265972, 2024). "Thymoquinone (TPL) is a natural product isolated from traditional herbal medicine, and research has found that TPL eliminates head and neck cancer cells through inducing pyroptosis mediated by gasdermin E (GSDME)." (PMID 38202657, 2023). "A recent study has indicated that GSDME ablation impaired the tumor-suppressive activity in head and neck cancer." (PMID 36457716, 2022). "Triptolide eliminates head and neck cancer cells through inducing gasdermin E (GSDME) mediated pyroptosis." (PMID 34108030, 2021). "In this study, we demonstrated that TPL treatment robustly eliminated head and neck cancer cells through GSDME-dependent pyroptosis." (PMID 34108030, 2021). "Our data showed that GSDME is the major executor responsible for TPL induced pyroptosis in head and neck cancer cells." (PMID 34108030, 2021). "In this study, we showed that TPL eliminated head and neck cancer cells mainly through GSDME-mediated pyroptotic cell death." (PMID 34108030, 2021). "The natural product triptolide eliminates head and neck cancer cells by inducing GSDME-mediated pyroptosis; however, the mechanism of this remains unclear." (PMID 36827109, 2023). "Pyroptosis of head and neck cancer cells was regulated by Bax–Bad–caspase-3 because the inhibition of Bax and Bad could weaken the activation of gasdermin E, thereby preventing gasdermin E-mediated pyroptosis." (PMID 36497206, 2022). "Triptolide (TPL), a natural diterpenoid epoxide derived from a traditional Chinese herb, reduced the expression of c-myc and mitochondrial HK2 in head and neck cancer cells and activated the BAD/BAX-caspase 3-GSDME cascade, triggering GSDME-mediated pyroptosis." (PMID 36339566, 2022). "TPL also suppressed NRF2/SLC7A11 axis and induced ROS accumulation in cancer cells, thus synergized with erastin to kill head and neck cancer cells, regardless of the expression status of GSDME." (PMID 34108030, 2021).
ovarian carcinoma (12 papers, 2020 to 2026). A malignant neoplasm originating from the surface ovarian epithelium. "Among the cytokines most highly regulated by the ET-1/ETAR-activated GSDME/ZEB1 signaling network, we noted interleukin (IL)-6, a gatekeeper of cancer cell/TME communication implicated in ovarian cancer growth, metastasis and immune evasion." (PMID 41545335, 2026). "Given that GSDME gene expression has been associated with EMT across distinct forms of cancer, including ovarian cancer, we evaluated the functional correlation of GSDME with the aggressive nature of HG-SOC." (PMID 41545335, 2026). "Recent evidence demonstrates that CBL0137 stimulates mitochondrial ROS production, BAX accumulation, and cyt c release to trigger caspase-3/GSDME-mediated pyroptosis in ovarian cancer cells." (PMID 38104141, 2023). "Among GSDMs, ubiquitous expression of GSDME has been reported in ovarian cancer." (PMID 41545335, 2026). "BI.2536 could induce GSDME-dependent pyroptosis concurrent with caspase-3-mediated apoptosis in ovarian cancer." (PMID 41007849, 2025). "GSDME-mediated pyroptosis induced by BI 2536 was shown to be antitumorigenic in ovarian cancer." (PMID 36016611, 2022). "Thus, BI 2536 induced pyroptosis in ovarian cancer through the caspase-3/GSDME pathway." (PMID 36016611, 2022). "As a result, our study found a promising agent for ovarian cancer and illustrated that it can induce pyroptosis through the caspase-3/GSDME pathway, which may have reasonable prospects in overcoming the drug resistance of ovarian cancer and improving the outcomes of these patients." (PMID 36016611, 2022). "In ovarian cancer, CBL0137 can activate ROS/BAX signalling and promote caspase-3/GSDME-dependent pyroptosis." (PMID 39616223, 2024). "In the genes that code for GSDMC, GSDMD, GSDME, and PJVK, ovarian cancer has the highest rate of copy number variation events of any cancer type." (PMID 37752941, 2023). "Through miRNA, these lncRNAs are connected with PRGs such as IRF1, NOD1, GSDMC, NLRP1, PLCG1, GSDME and GZMB to construct a pyroptosis related ceRNA regulatory network in ovarian cancer." (PMID 37859811, 2023). "NOB, a polymethoxyflavonoid, stimulates traditional autophagy, ROS production, and a decline in MMP, all of which contribute to initiating GSDMD/GSDME‐mediated pyroptosis and upregulating the expression of IL‐1β and ASC in ovarian cancer." (PMID 37752941, 2023). "In the gasdermin family, GSDMA (logFC=1.38557, FDR=5.23e-15) and GSDMC (LogFC=2.298323, FDR=2.06e-38) was significantly overexpressed in ovarian cancer, while the expression of GSDMD (logFC=-1.10275, FDR=8.25e-30) and GSDME (logFC=-2.29572, FDR=1.54e- 46) was significantly lower in ovarian cancer." (PMID 37859811, 2023). "Thus, we discovered many unproven pyroptosis related regulatory axes in ovarian cancer, such as KRT7-AS—has-miR-205—GSDMC, LINC01094—has-miR-330-3p—IRF1, ZNF32-AS2—has-miR-214—GSDME, and MYCNOS—has-miR-150—NLRP1." (PMID 37859811, 2023). "In their TMEs, ovarian cancer patients have greater GSDMD and lower GSDME protein levels." (PMID 37752941, 2023). "However, exceptions exist, as autophagic inhibition in ovarian cancer cells hindered pyroptosis by downregulating active GSDMD and GSDME." (PMID 38007535, 2023). "However, only AOX1 of top five down-regulated genes was verified to be decreased in expression for expanding sample of ovarian cancers, with that of REEP1, BNC1, HAND2, and GSDME unchanged." (PMID 33135729, 2020). "Interestingly, a study revealed that bexarotene treatment activated caspase-4 instead of caspase-3 and encouraged GSDME-dependent pyroptosis in ES2 cell line, indicating that bexarotene may be a novel agent for treating ovarian cancer." (PMID 38104141, 2023).
ovarian carcinoma (continued). "The latest small molecule inhibitor, BI 2536, inhibits the proliferation of ovarian cancer cells, triggers cell cycle halt at the G2/M phase, and accumulates CD8+ T lymphocyte cells at tumor sites via initiating pyroptosis in ovarian cancer through the caspase 3/GSDME pathway." (PMID 37752941, 2023). "At present, studies have shown that GSDMD 7, 33 and GSDME 32, 33 are the key targets that cause pyroptosis in ovarian cancer cells, while GSDMA and GSDMC have not been proven to be involved in the pyroptosis of ovarian cancer cells, which is consistent with our analysis results." (PMID 37859811, 2023).
atherosclerosis (11 papers, 2023 to 2025). A disease characterized by the build-up of fatty material and calcium deposition in the arterial wall resulting in partial or complete occlusion of the arterial lumen. "GSDME-mediated pyroptosis has been linked to the progression of atherosclerosis, where macrophage pyroptosis and inflammation are suppressed when GSDME is blocked." (PMID 38645692, 2024). "Collectively, these results indicate that GSDME deficiency mitigates diet-induced atherosclerosis and inflammation in ApoE−/− mice." (PMID 36807553, 2023). "Our findings provide evidence of GSDME activation during the progression of atherosclerosis and confirm that the deficiency of GSDME exhibited significant effects on reducing atherogenesis and diminishing vascular inflammation in ApoE−/− mice." (PMID 37761020, 2023). "In conclusion, we have demonstrated that GSDME expression is upregulated during atherosclerosis, and GSDME deficiency reduces pyroptosis-related proinflammatory cytokine release in atherosclerotic plaques." (PMID 36807553, 2023). "Meanwhile, GSDME deficiency attenuates the progression of atherosclerosis in ApoE−/− mice fed with a high-fat diet." (PMID 36807553, 2023). "GSDME expression is upregulated in atherosclerotic lesions, and GSDME deficiency suppresses pyroptosis-related inflammation and decreases the development of atherosclerosis." (PMID 36807553, 2023). "To test the hypothesis that GSDME-mediated pyroptosis aggravates the progression of atherosclerosis, we generate ApoE and GSDME dual deficiency mice." (PMID 36807553, 2023). "Experiments conducted on mice and HUVECs demonstrated that SR-717 administration could partially counteract the inhibitory effects of GSDME deficiency on atherosclerosis, vascular inflammation, and ox-LDL-induced endothelial cell inflammation." (PMID 37761020, 2023). "Importantly, caspase 3, an upstream molecule of GSDME, has been identified as an independent risk factor for atherosclerosis in clinical investigations." (PMID 37761020, 2023). "Utilizing in situ imaging and HE staining, we observed that the activation of the STING pathway led to an enlargement of the plaque area in both GSDME−/−/ApoE−/− and ApoE−/− mice, thereby counteracting the suppressive influence of GSDME deficiency on atherosclerosis progression." (PMID 37761020, 2023). "For example, STAT3, a transcription factor activated by inflammatory cytokines, was reported to increase GSDME expression in vascular endothelial cells during atherosclerosis." (PMID 41550939, 2025). "In summary, an increasing body of research suggests that GSDME influences the progression of atherosclerosis by promoting pyroptosis in key cells." (PMID 41550939, 2025). "Another study of atherosclerosis focused on gasdermin E (GSDME), a protein with a role in cellular inflammation and pyroptosis." (PMID 40461989, 2025). "This research underscores the pivotal role of GSDME, an often overlooked member of the gasdermin family, in the pathogenesis of atherosclerosis, specifically in endothelial cells." (PMID 37761020, 2023). "Given this context, our study was geared toward identifying alternative mechanisms by which GSDME exacerbates vascular inflammation and atherosclerosis beyond the scope of cell pyroptosis." (PMID 37761020, 2023). "To investigate the transcriptome of human atherosclerotic plaques as well as the localization of GSDME in atherosclerosis, we performed single-cell RNA sequence analysis cells from advanced human carotid plaques with calcification or hemorrhage." (PMID 36807553, 2023). "Atherosclerosis also showed increased levels of IL-1β, caspase 3, and GSDME compared with control vessels, as indicated by immunohistochemistry." (PMID 36807553, 2023). "The compelling evidence presented here broadens our understanding of endothelial inflammation within the context of atherosclerosis, highlighting the nuanced interplay between GSDME, mitochondrial dysfunction, and the STING pathway." (PMID 37761020, 2023).
atherosclerosis (continued). "Intriguingly, when treated with SR-717, a specific STING agonist, there was a partial reversal of the inflammation and atherosclerosis suppression induced via GSDME inhibition, evident in both in vivo and in vitro settings." (PMID 37761020, 2023). "As we continue to unravel these mechanisms, the urgency to develop and validate GSDME protein inhibitors in mouse atherosclerosis models becomes evident." (PMID 37761020, 2023). "This study presents compelling evidence for GSDME’s role in endothelial cells, contributing to vascular inflammation and the onset of atherosclerosis, as demonstrated both in animal models and at the cellular level." (PMID 37761020, 2023). "Collectively, the present study provides initial evidence that GSDME activation aggravates pyroptosis-related inflammation in atherosclerotic lesions and contributes to the development of atherosclerosis." (PMID 36807553, 2023). "Human atherosclerosis single-cell transcriptome analysis demonstrates that GSDME is mainly expressed in macrophages." (PMID 36807553, 2023). "This underscores the importance of endothelial cells when considering GSDME’s influence on atherosclerosis." (PMID 37761020, 2023). "Taken together, We indentify that GSDME mediates pyroptosis-related inflammation in atherosclerosis and can serve as a potential targets to treat atherosclerosis." (PMID 36807553, 2023). "Given these insights, future research should focus on uncovering additional potential pathways, aiming to deepen our understanding of the intricate mechanisms through which GSDME affects endothelial inflammation and atherosclerosis." (PMID 37761020, 2023). "In the atherosclerosis-prone ApoE−/− mice, GSDME protein and mRNA levels were significantly increased after feeding high-fat diet for 12 wk." (PMID 36807553, 2023). "Through its caspase-3-dependent activation and pore-forming capacity, GSDME converts apoptotic signals into secondary pyroptosis, amplifying tissue inflammation and injury in conditions such as atherosclerosis, myocardial infarction, cardiomyopathy, and pulmonary hypertension." (PMID 41550939, 2025). "Furthermore, silencing endogenous STAT3 reduced GSDME expression, further suggesting a potential therapeutic approach for atherosclerosis." (PMID 41550939, 2025). "However, as atherosclerosis progresses, caspase-mediated cleavage of GSDME mediates membrane permeabilization and secondary necrosis." (PMID 41463394, 2025). "Based on the increased expression of GSDME in atherosclerosis, we wondered whether GSDME ablation suppresses the development of atherosclerosis." (PMID 36807553, 2023). "However, our findings bring to light a novel aspect, revealing that GSDME mediates endothelial inflammation, thereby promoting vascular inflammation and the initiation of atherosclerosis." (PMID 37761020, 2023). "Here the authors show that, in human atherosclerotic plaques and mouse models, GSDME and pyroptosis promote atherosclerosis and inhibition of these pathways could reduce pathology associated with atherosclerotic disease." (PMID 36807553, 2023). "Thus, our findings suggest the STING pathway as a potential downstream effector in the cascade of GSDME-induced endothelial inflammation and atherosclerosis." (PMID 37761020, 2023). "Interestingly, this activation counteracted some of the protective effects of GSDME deficiency, suggesting that the STING pathway operates downstream of GSDME in mediating endothelial inflammation and atherosclerosis." (PMID 37761020, 2023). "GSDME may serve as a potential therapeutic target for treating inflammation-related diseases, such as atherosclerosis." (PMID 36807553, 2023). "This study explores the transcriptional mechanisms of GSDME during atherosclerosis development and indicates that GSDME-mediated pyroptosis in the progression of atherosclerosis could be a potential therapeutic approach for atherosclerosis." (PMID 36807553, 2023).